ALB (albumin)
Diseases named in the same sentence as ALB in open-access papers (continued):
Sharing a sentence is not in itself a finding about the gene and the disease.
vitamin D deficiency (continued). "In contrast, HCV antibody seropositivity (OR = 0.50; 95% CI: 0.31, 0.81) and HIV seropositivity (OR 0.67; 95% CI: 0.49, 0.92) were associated with lower odds of vitamin D deficiency as were season of blood draw, multivitamin intake and higher serum albumin." (PMID 24756000, 2014). "Plasma albumin was elevated in patients with normal 25-OH D compared to those with vitamin D deficiency." (PMID 24800209, 2014). "Albumin excretion rate (73.1 to 57.1, p = 0.22) in vitamin D insufficiency/deficiency group." (PMID 40134933, 2025). "In this regard, previous research has suggested that vitamin D deficiency may be associated with lower albumin and/or pre-albumin levels, indicating a possible link between vitamin D status and protein malnutrition." (PMID 37410265, 2024). "Serum albumin was suggested to be a significant predictor of vitamin D deficiency, thus a lower serum albumin level may suggest possible poorer nutritional management compared to healthy controls." (PMID 38915402, 2024). "A prospective study observed that urinary albumin excretion decreased significantly (from 127.05 ± 84.79 to 104.81 ± 74.05 μg/mg) in patients with type I DM with microalbuminuria with vitamin D deficiency after oral administration of 0.25 μg calcitriol per day for 6 months." (PMID 36835159, 2023). "Vitamin D deficiency is frequent among hemodialysis patients, and a cross-sectional study has found a positive correlation between vitamin D levels and nutritional parameters (serum albumin and serum hemoglobin)." (PMID 36562038, 2022). "The decreased VDBP mRNA expression level along with significantly lower serum albumin level were found in active PTB patients compared to healthy controls, implying that VDBP, albumin deficiency could play a role in vitamin D deficiency states." (PMID 33882819, 2021). "Vitamin D deficiency can be a predictive agent for low serum albumin levels." (PMID 33898881, 2021). "Vitamin D deficiency is implicated in reduced serum albumin concentrations." (PMID 26610599, 2015). "Hence, serum ionic/free calcium, which is non-albumin bound calcium, is expected to be higher in vitamin D deficiency conditions." (PMID 26610599, 2015). "Lower serum albumin is associated with inadequate protein and caloric intake, as well as inflammation, all of which may be present in a population of IDUs and contributing to vitamin D deficiency." (PMID 24756000, 2014). "Serum TP, composed of ALB and GLOB, serves as an important indicator of inflammation and nutritional status, while Ca and P are commonly used as indicators of vitamin D deficiency." (PMID 41585527, 2025). "More than half of ICU patients had vitamin D deficiency, and we also found that their levels of VDBP, calcium, and albumin were lower." (PMID 39272727, 2024). "Compared to those with sufficient vitamin D levels, those with vitamin D deficiency had higher MELD-Na scores and waiting time for LT but lower albumin levels." (PMID 38030697, 2023). "In the multivariable analysis, young age, female gender, low albumin level, high PTH level, and high SOFA scores were significantly associated risk factors for vitamin D deficiency." (PMID 34966771, 2021). "Age, gender, albumin level, PTH level, and SOFA score were significantly associated with vitamin D deficiency in these patients." (PMID 34966771, 2021). "Young age, female gender, low albumin level, high PTH level, and high SOFA score are significantly associated risk factors for vitamin D deficiency." (PMID 34966771, 2021). "On the univariate analysis, the following eight variables were significantly related to frailty: age, BMI, LC, serum levels of albumin, BCAA, and 25(OH)D, PT-INR, and vitamin D deficiency." (PMID 33322706, 2020). "Non-black race, fall/winter season, multivitamin intake, higher serum albumin, HCV seropositivity and HIV-infection were associated with significantly lower odds of vitamin D deficiency." (PMID 24756000, 2014).
vitamin D deficiency (continued). "Whereas in patients with vitamin D deficiency, age, BUN, and iPTH were higher, serum albumin, calcium levels were lower." (PMID 23737771, 2013). "Moreover, NDMM patients who exhibited a vitamin D deficiency status below 50 nmol/L (20 ng/mL) demonstrated increased mean values for serum C-reactive protein (CRP) and creatinine, as well as decreased serum albumin levels." (PMID 37513645, 2023). "A cross-sectional study observed a non-significant reduction in urinary albumin excretion in patients with type II DM with albuminuria with vitamin D deficiency receiving 0.5 μg of calcitriol daily for 8 weeks (p = 0.22)." (PMID 36835159, 2023). "Moreover, this study revealed that young age, female gender, low albumin level, high PTH level, and high SOFA score are associated with vitamin D deficiency." (PMID 34966771, 2021). "According to the multivariable analysis, young age, female gender, low albumin level, high parathyroid hormone (PTH) level, and high sequential organ failure assessment (SOFA) score were significantly associated risk factors for vitamin D deficiency." (PMID 34966771, 2021). "Nutritional status was similar between study patients with and without vitamin D deficiency based on serum levels of albumin and nPCR." (PMID 32371900, 2020). "By univariate analysis, vitamin D deficiency (<10 ng/mL) was significantly associated with higher levels of HBV viral load, AST, TBIL, and prolonged PT, but lower levels of cholesterol, HDL-c, LDL-c, albumin, calcium, and thrombocytes." (PMID 27399065, 2016). "Patients with vitamin D deficiency had lower serum albumin levels compared to those with non-deficient serum vitamin D levels (p = 0.05)." (PMID 25774530, 2015). "Urinary albumin excretion (127.05 to 104.81 μg/mg, p < 0.05), urine MCP-1/creatinine (99.38 to 89.57 ng/mmol, p < 0.05), urine TGF-β/creatinine (79 to 72.33 ng/mmol, p < 0.05), TNF-α (57.7 to 47.09 pg/mL, p < 0.05), IL-6 (44.04 to 39.88 pg/mL, p < 0.05) in vitamin D insufficiency/deficiency group." (PMID 40134933, 2025). "In addition, patients with vitamin D deficiency had lower serum albumin levels compared to those with non-deficient serum vitamin D levels, the finding being borderline significant (p = 0.06)." (PMID 26704811, 2015). "In addition to black race and season, we observed significantly greater odds of vitamin D deficiency associated with lack of multivitamin intake and with lower serum albumin; the latter, suggests that poor nutritional status may have contributed." (PMID 24756000, 2014). "Indeed, both had normal serum albumin-adjusted total calcium serum levels and high serum levels of PTH (106 and 102 pg/mmol, respectively (normal range: 15–65)) without vitamin D deficiency." (PMID 31979085, 2020).
hepatorenal syndrome (74 papers, 2008 to 2026). Hepatorenal syndrome is a form of impaired kidney function that occurs in individuals with advanced chronic liver disease. "The association of terlipressin with albumin in the treatment of hepato-renal syndrome was more effective in improving the renal function when compared to albumin alone." (PMID 40150093, 2025). "In patients with features of hepato-renal syndrome, intravenous albumin infusion and dopamine and nor-adrenaline drips were given." (PMID 19248644, 2009).
prostate carcinoma (72 papers, 2008 to 2026). A carcinoma that arises from epithelial cells of the prostate gland. "Multivariate analysis showed that ALP (OR = 0.991, P < .05) was an independent risk factor for bone metastasis in prostate cancer after adjusting for Age, ALB, and FIB." (PMID 42299585, 2026). "According to the well-known Swedish AMORIS trial, ALB levels were found to be favorably associated with GS 4 + 3 prostate cancer and negatively associated with high-risk or metastatic prostate cancer 14 years before diagnosis." (PMID 38384810, 2024). "Another study also indicated that prostate cancer patients with low serum albumin levels and high body mass index (BMI) had a high risk of death." (PMID 37571238, 2023). "The new results demonstrate that when delivered in the complex with serum albumin in vitro, palmitic acid suppresses the secretion of exosomes and exosome-associated molecules characteristic of prostate cancer." (PMID 32545453, 2020). "Thus, GFR, alkaline phosphatase, and albumin were detected in this study to reflect renal and liver functions in patients with high-risk prostate cancer who received Boennuokang® leuprorelin acetate microspheres-based treatment as neoadjuvant therapy." (PMID 40177247, 2025). "Additionally, several indices involved with serum albumin have been shown to predict prostate cancer risk and prognosis." (PMID 37571238, 2023). "A low serum albumin level induces less albumin-binding testosterone, which may lead to an increased risk of prostate cancer incidence, recurrence, progression, and poor outcomes." (PMID 37571238, 2023). "In addition, ALB is considered to reflect liver function and in metastasized, castration-resistant prostate cancer, and lowered levels of ALB is known to associate with increased tumor burden." (PMID 36897911, 2023). "This study compares the antitumor and cytotoxic effects of albumin-coated AgNPs (AgNPs-Alb) versus AgNPs on human prostate cancer cell lines." (PMID 41900824, 2026). "Serum TPSA, FPSA, FIB, ALB, ALP and GS have significant diagnostic value in identifying prostate cancer bone metastasis." (PMID 42299585, 2026). "This study aimed to investigate the role of the hemoglobin-albumin-lymphocyte-platelet (HALP) score in detecting prostate cancer in patients undergoing transurethral resection of the prostate (TURP)." (PMID 38716011, 2024). "In our investigation, we sought to assess the utility of the HALP score, which comprises hemoglobin, albumin, lymphocytes, and platelets, as a predictive tool for the occurrence of prostate cancer in patients undergoing TURP." (PMID 38716011, 2024). "The HALP score comprises four biomarkers (hemoglobin, albumin, lymphocyte, and platelet) and has been used as a prognostic marker for many cancers, including prostate cancer." (PMID 37571238, 2023). "Monodisperse solutions of SeNPs capped with bovine serum albumin (BSA) were shown to slow down the migration capacity of aggressive prostate cancer cells compared to polydisperse solutions of SeNPs capped with chitosan." (PMID 38063696, 2023). "It has a 4-iodophenyl butanoic group that interacts with serum albumin to elongate the circulation time of the compound and subsequently increase the uptake of the therapeutic radiopharmaceutical by prostate cancer cells." (PMID 36551710, 2022). "A literature search process was performed (“prostatic cancer”, “albumin”, “globulin”, “albumin to globulin ratio”) following the PRISMA guidelines." (PMID 36232828, 2022). "The aim of our meta-analysis is to analyze data available in the literature regarding a possible prognostic value of the albumin to globulin ratio (AGR) in prostate cancer (PC) patients." (PMID 36232828, 2022). "A DCE-MRI study assessing anti-PDGFR therapy effects in a prostate cancer bone metastasis model with biotin-labeled albumin-Gd-DTPA showed a reduction in vascular permeability and provided insights into the role played by VEGF in anti-PDGFR therapy." (PMID 28415647, 2017).
prostate carcinoma (continued). "The lack of association between inflammatory markers and specific cancer risk was further shown when we investigated serum CRP, leukocytes, albumin, and haptoglobin in relation to prostate cancer." (PMID 26284119, 2015). "Previous studies have shown that serum albumin is associated with prostate cancer (PCa), but not with prostate-specific antigen (PSA) levels in populations without PCa history." (PMID 36950094, 2023). "Moreover, it has been shown that the albumin levels were significantly lower in prostate cancer patients than those with BPH (p = 0.0001)." (PMID 37571238, 2023). "Our findings suggested that serum albumin has a negative causal association with the risk of prostate cancer [odds ratio (OR) = 0.78, 95% confidence interval (CI): 0.68–0.91, p = 0.001]." (PMID 37441531, 2023). "Moreover, another study showed that men with a high albumin level tended to have a low PSA and a lower risk of advanced prostate cancer." (PMID 37571238, 2023). "Factors associated with an increased risk of prostate cancer mortality included age; high PSA; current or ex-smoker; ischaemic heart disease; high C reactive protein; high ferritin; low haemoglobin; high blood glucose and low albumin." (PMID 33579772, 2021). "Some anti-cancer drugs such as doxorubicin might bind albumin to reach the target organ and play a therapeutic role in prostate cancer." (PMID 33859877, 2021). "At the same time, we note that a higher concentration can promote proliferation of cultured prostate cancer cells, as demonstrated by the recent work, where 100 μM albumin-coupled palmitic acid was tested and found to increase the cells’ proliferation by approximately 10%." (PMID 32545453, 2020). "Moreover, DCE-MRI monitoring of sorafenib therapy effects on experimental prostate carcinomas with albumin-(Gd-DTPA) 35 showed significant correlations with anti-angiogenic, anti-proliferative and proapoptotic effects determined immunohistochemically." (PMID 28415647, 2017). "The comparison of prostatic volume, total testosterone, sex hormone binding globulin, free testosterone, bioavailable testosterone and albumin showed that patients with cancer of the prostate had significantly greater levels of free testosterone (p=0.043) and bioavailable T (p=0.049)." (PMID 27532110, 2016). "More recently, systemic inflammation based prognostic scores such as the modified Glasgow Prognostic Score (mGPS, a combination of C-reactive protein and albumin), have been developed and found to have significant prognostic value in one-year and five-year survival from prostate cancer." (PMID 23768149, 2013). "High sensitive C-reactive protein (hs-CRP) and albumin levels were assessed in 1679 prostate biopsy patients in order to study the association between HAR—high sensitive C-reactive protein to albumin ratio—and prostate cancer to assess HAR’s importance in prostate biopsy." (PMID 38384810, 2024). "Similarly, although higher serum levels of free fatty acids are associated with prostate cancer, prostate disease outcomes through their impact on the Zn carrier capability of albumin are not known." (PMID 36551962, 2022). "Prostate cancer patients with high pre-treatment PNI values, corresponding to high serum albumin, have better response rates with treatments and survival outcomes, including prostate cancer progression-free survival and overall survival." (PMID 37571238, 2023). "Another albumin-related index is the prognostic nutritional index (PNI), which has been used as a prognostic marker for predicting survival in prostate cancer patients." (PMID 37571238, 2023). "AuNPs coated with human albumin multilayer and further decorated with DOTA chelator and BBN peptide acting as targeted therapeutic agent for prostate cancer cells (i.e., PC-3)." (PMID 35631646, 2022). "Recently, many studies have shown that albumin is a useful prognostic predictor in various malignancies such as UTUC, HCC, and prostate cancer." (PMID 33376729, 2020).
prostate carcinoma (continued). "Previous studies have reported that ALB was a reliable predictive tool in various cancers, including HCC, RCC, and prostate cancer 25-27." (PMID 31632493, 2019). "Twenty-four hours later, the amount of albumin-EB complex retained in plasma vs. accumulated in liver, kidney, or CWR-22Rv1 prostate cancers determined." (PMID 25193858, 2014). "To evaluate the generalizability of RAiDER, we performed analogous biodistribution assays using a syngeneic murine model of prostate-specific membrane antigen (PSMA)–expressing prostate cancer (RM1.PSMA) by treating tumor-bearing mice with albumin-conjugated caged exatecan and [177Lu]Lu-PSMA-617." (PMID 39753366, 2025). "All albumin fusions were able to activate T cells when co-incubated with PSMA-expressing cell lines and mediate T-cell cytotoxicity against PSMA-expressing prostate cancer cell lines." (PMID 36243890, 2022). "Hb, albumin, prostate volume, and prostate transitional zone volume were significantly lower in the prostate cancer diagnosis group than in the non-prostate cancer diagnosis group (P < 0.05)." (PMID 33910525, 2021). "It is also consistent with PET studies that revealed small differences in 89Zr-DFO-albumin uptake in three xenograft models of prostate cancer at 1 h but not at 20 h, despite marked histological differences." (PMID 32960353, 2020). "Third, neither istaroxime nor digoxin or ouabain were capable of blocking mAR dependent apoptosis triggered by testosterone-albumin conjugates in prostate cancer cells and vice versa (data not shown)." (PMID 27027435, 2016). "The serum TPSA, FPSA, FIB, ALP and GS levels of patients in the prostate cancer bone metastasis group were higher than those of patients in the prostate cancer without bone metastasis group, while the ALB level in the bone metastasis group was lower than that in the non-bone metastasis group." (PMID 42299585, 2026). "Furthermore, the database does not include additional serum markers including haemoglobin, albumin, alkaline phosphatase or lactate dehydrogenase, nor the quantification of disease volume, which are documented prognostic factors in prostate cancer." (PMID 35492221, 2022). "Hemoglobin, age, and LDH and albumin are not specific for prostate cancer." (PMID 35395766, 2022). "A recent study based on transcriptome analysis of prostate cancer tissues showed that SPINK1 overexpressin prostate cancers are characterized by a peculiar gene expression signature, involving the expression of genes typically expressed in the gastrointestinal tract, such as albumin gene." (PMID 31366128, 2019). "First, patients were selected on the basis of availability of PSA, C-reactive protein and albumin, therefore this cohort of patients might not be representative of all the prostate cancer patients diagnosed and treated in the area." (PMID 23768149, 2013).